AR (androgen receptor)
Diseases named in the same sentence as AR in open-access papers (continued):
Sharing a sentence is not in itself a finding about the gene and the disease.
prostate carcinoma (continued). "Hormone-associated tumors, such as ER + breast cancer and androgen receptor-positive (AR+) prostate cancer, are mainly dependent on hormone receptor (HR) signaling to sustain tumor cell growth and survival." (PMID 37211598, 2023). "Resistance to androgen deprivation therapy is inevitable, and molecular mechanisms driving castration-resistant prostate cancer (CRPC) primarily involve alterations in AR expression and activity." (PMID 36983083, 2023). "The transcription factor ONECUT2 (OC2) is a master transcriptional regulator operating in metastatic castration-resistant prostate cancer that suppresses androgen receptor activity and promotes neural differentiation and tumor cell survival." (PMID 37484909, 2023). "Therapeutic interventions for advanced prostate cancer (PCa) are based on the inhibition of the androgen receptor (AR) and downstream of the signaling pathways." (PMID 36983083, 2023). "Remarkably, EGCG and quercetin have shown to sensitize prostate-cancer cells to Docetaxel and Enzalutamide, among others, by improving their anti-proliferative effect and by inhibiting androgen receptor signaling." (PMID 37299500, 2023). "Androgens and the androgen receptor (AR) are required for normal growth and function of the prostate gland and are critical for all stages of prostate cancer development and progression." (PMID 38131032, 2023). "In prostate cancer cells (LNCaP), FM-miR-34a induced a similar downregulation of AR protein expression and a comparable inhibition of invasion as cells transfected with PM-miR-34a." (PMID 37666938, 2023). "We established a CBZ-resistant AR-positive prostate cancer model, LNKO6CR, which was derived by incubating LNCaP under androgen ablation conditions for 6 months and subsequently incubating with gradually increasing CBZ concentrations for 12 months." (PMID 34593983, 2023). "Treatments currently in use mainly aim at tumor debulking or targeting AR; the latter representing a crucial oncogenic driver of prostate cancer." (PMID 36899938, 2023). "Prostate cancer (PCa) is the most prevalent male-related malignancy in the western world and is driven largely by androgen receptor (AR) signaling." (PMID 36674820, 2023). "Prior research has demonstrated that AR-mediated autophagy induction is essential for the proliferation and viability of prostate cancer cells." (PMID 37834333, 2023). "A plenty of AR antagonists have been developed for the treatment of advanced prostate cancer, exemplified by enzalutamide." (PMID 37261210, 2023). "YAP1 also regulates the self-renewal property of prostate cancer cells and is negatively regulated by AR via YAP1 promoter methylation." (PMID 37282627, 2023). "Most metastatic prostate cancers will respond initially to therapies that interfere with the androgen receptor (AR) signaling axis." (PMID 36650836, 2023). "Bic antagonized the effect of DHT on AR-mediated gene transactivation and regulation in prostate cancer cell lines." (PMID 38091304, 2023). "The growth of primary prostate cancer is dependent on the androgen receptor (AR) and AR signalling is critical to prostate cancer progression." (PMID 37563360, 2023). "p300 also regulates transcriptional processes in prostate cancer; on the one hand, p300 recognise phosphorylated AR, which promotes subsequent AR acetylation at K609, thereby facilitating transcription." (PMID 36979352, 2023). "The clinical outcomes and gene expression profiles of prostate cancer patients support the clinical benefits of these two types of AR antagonists." (PMID 37025180, 2023). "The LNCaP cell line is a prostate cancer cell line whose growth is highly affected by the expression and activity of AR." (PMID 37794090, 2023). "ARCC‐4 showed good in vitro potency including low‐nanomolar DC50 (half‐maximal degradation concentrations) value, moderate inhibition on proliferation of prostate cancer cells with better antiproliferative effects on enzalutamide‐resistant AR mutant cells." (PMID 37261210, 2023).
prostate carcinoma (continued). "In prostate cancer, the redistribution of coactivators in the common super-enhancer region is dependent on the ratio of AR to MYC levels." (PMID 37443779, 2023). "Genes involved in lysosomal biogenesis and function as well as core autophagy genes were recently identified as transcriptional targets of AR in prostate cancer." (PMID 37874216, 2023). "To determine the role of the androgen analog, R1881, on the expression of MALT1 in AR-positive prostate cancer cells, we treated two ARFL-positive prostate cancer cells, LNCaP and 22Rv1, with various concentrations of R1881 for 24 h." (PMID 37047218, 2023). "It has been shown to be an AR inhibitor with a low toxicity profile that inhibits prostate cancer cell growth." (PMID 37569712, 2023). "Androgen receptor (AR) activation and repression dual-functionality only became known recently and still remains intriguing in prostate cancer (PCa)." (PMID 37828515, 2023). "The importance of estrogen regulates (ER) for female breast cancer is similar to AR for male prostate cancer." (PMID 36733714, 2023). "Both cell lines were established from cells isolated from the lymph nodes of patients with prostate cancer, express the AR and regulate the KLK3 gene in response to androgens." (PMID 37082578, 2023). "Independent of promoting mitotic arrest, MSAs can suppress the nuclear accumulation of androgen receptor (AR), which is the driving force for prostate cancer cell growth and progression." (PMID 37444418, 2023). "Androgen receptor (AR) signalling plays a pivotal role in the development and progression of prostate cancer." (PMID 37099169, 2023). "Overexpression of NK1R in epithelial prostate cancer cells was able to induce a shift of lineage plasticity, leading to the reduction of AR and PSA levels, the gain of the expression of CgA, ENO2, AURKA, N-Myc, MYT1, and SRRM4." (PMID 37385990, 2023). "Most data on the importance of PI3K and AKT in the modulation of AR function and effects on prostate cancer proliferation were generated with specific inhibitors, thus providing strong evidence for the relevance of the pathway for therapeutic targeting." (PMID 36768610, 2023). "The efficacy of these new drugs proves that AR is a principal driver of prostate cancer progression in patients with CRPC." (PMID 37744273, 2023). "The downregulation of AR expression in the prostate cancer cells resulted in recruiting more CD4+ T cells, providing a feedback loop for this interaction between the prostate cancer cells and CD4+ T cells enforcing invasiveness of the prostate cancer." (PMID 36836690, 2023). "selected epigenetically altered genes in prostate cancer and found AR, GSTP1, RARB, SPARC, TIMP3, and NKX2-5 to be hypermethylated in AA patients." (PMID 36937425, 2023). "Inhibition of androgen receptor (AR) signaling has been the mainstay of treatment of advanced prostate cancer (PCa) for the past 80 years." (PMID 37027449, 2023). "As a proof of principle of experimental utility, we manipulated the expression of the androgen receptor (AR), a gene central to prostate cancer biology." (PMID 37999103, 2023). "It has also been shown that ER-β-specific agonist in combination with AR targeting therapies decreases the survival of castrate-resistant prostate cancer (CRPC) cells." (PMID 36891053, 2023). "Previous reports have indeed outlined that crosstalk between androgen receptor (AR), NF-κB, and Wnt/β-catenin signaling is imperative in increasing the metastasis and progression of prostate cancers." (PMID 38348349, 2023). "The inhibition of HDAC6 by SFN in prostate cancer cells increases the acetylation state of heat shock protein 90 (Hsp90) and decreases the expression of the androgen receptor (AR)." (PMID 36900446, 2023). "Biochemical and RNA-seq data are both consistent with PARP7 operating as the androgen-regulated mono-ADP-ribosyltransferase that modifies nuclear AR in prostate cancer cells." (PMID 37077937, 2023).
prostate carcinoma (continued). "Maintaining of AR protein and activation of the AR signaling pathway are in every stage of prostate cancer, even after androgen deprivation therapy." (PMID 37152995, 2023). "The interaction promotes MDM2-mediated ubiquitination of AR and its subsequent proteasomal degradation resulting in growth inhibition of prostate cancer cells." (PMID 36831540, 2023). "The earliest reports of AR imaging studied radiobrominated [77Br] and radioiodinated [125I] androgens in prostate cancer." (PMID 37175938, 2023). "Early studies have indicated that androgen-independent prostate cancer cells and xenografts present an elevated constitutive NF-κB activity, suggesting a negative regulation between AR and NF-κB signaling." (PMID 37047218, 2023). "While PMEPA1 isoforms a and d are the main isoforms that inhibit TGF-β signaling, the main isoform that inhibits AR signaling in prostate cancer cells is PMEPA1-b." (PMID 38173834, 2023). "While both androgen-receptor-positive and “castration-resistant” prostate cancer are responsive to these approaches, the development of resistance is an almost inevitable outcome leading to the castration-resistant form of the disease." (PMID 37894395, 2023). "Our discoveries suggest that Sigma1 is a novel regulator of aberrant AR/ARV signaling in prostate cancer cells." (PMID 37874216, 2023). "The androgen receptor (AR) and its subsequent signaling pathways play important roles in the growth and progression of prostate cancer." (PMID 37118708, 2023). "To identify a new AR inhibitor, we screened 50,000 culture broths of microorganisms using the androgen-dependent growth of the human prostate cancer cell line LNCaP as a screening indicator." (PMID 37744273, 2023). "In hypoxia, GPI maintains glucose metabolism by redirecting the glucose from androgen/androgen receptor (AR)-dependent to hypoxia-induced glycolysis, attenuating chemotherapy efficacy in prostate cancer." (PMID 36781976, 2023). "Runt-related transcription factor 1 (RUNX1) correlates with poor prognosis in TNBC and is regulated by the AR in prostate cancer." (PMID 36766786, 2023). "As an example, upon comparing signaling as functions of prostate cancer development, it was clear that some gene networks are consistently similar (i.e. AR and FOXA1) whereas others are highly dependent on the ecosystem (i.e. MYC)." (PMID 37059746, 2023). "While the luminal epithelial lineage is AR-dependent and thought to exhibit less plasticity, primary prostate cancers almost exclusively exhibit luminal phenotype and AR dependence." (PMID 37018402, 2023). "In prostate cancer, androgen receptor activation mediates ETV1 expression, activating Twist1, leading to EMT and tumor metastasis." (PMID 37197420, 2023). "As AR and Myc are critical to the regulation of cell survival and proliferation in prostate cancer, we assessed the time course by which they are suppressed upon fimepinostat treatment in the 22Rv1 and LNCaP95 cell lines." (PMID 37823778, 2023). "Because AR and male sex hormones contribute to prostate carcinogenesis, hormone therapy is an essential option for prostate cancer patients." (PMID 37794090, 2023). "For instance, TMED3 was highly expressed in prostate cancer and metastatic prostate cancer, and high expression of TMED3 was associated with the expression of the androgen receptor and ERG oncogene." (PMID 36991473, 2023). "FOXA1 (Forkhead box A1) is known to be essential for the survival of normal prostate and prostate cancer tissue by maintaining AR signaling." (PMID 36711033, 2023). "DVL2 has been shown to enhance the metastatic potential of prostate cancer by upregulating expression of Wnt-3a, AR, and MMP." (PMID 37534375, 2023). "An alternative explanation, at least in prostate cancer cells, is that gene expression induced by AR and AHR creates a PARP7 dependency for cell growth." (PMID 37077937, 2023).
prostate carcinoma (continued). "ER, in addition to AR, plays an important biological function as a transcription factor and regulatory protein in prostate cancer (reviewed by 59–62)." (PMID 36936148, 2023). "We focus on the regulation of glutamine metabolism in prostate cancer through key pathways involving the androgen receptor pathway, MYC, and the PTEN/PI3K/mTOR pathway." (PMID 36959101, 2023). "To study how the drug-altered cell morphology affects the AI prediction, we cultured prostate cancer cells (LNCaP) and treated them with Enza, which impairs cell growth and alters cell metabolism through androgen receptor inhibition." (PMID 38026685, 2023). "Prostate cancer development requires androgen receptor (AR)-mediated signaling, which makes androgen deprivation therapy (ADT) the standard first-line treatment for patients with advanced disease." (PMID 37834162, 2023). "By comparing with 5,7,20-O-hydnocarpin Ds, chalcone-type flavonolignans, and taxifolin derivatives, 5,7,20-O-trimethylsilybin and its derivatives possess the highest potency and selectivity towards AR-positive LNCaP prostate cancer cell line." (PMID 37111288, 2023). "In vitro study results revealed that hampering the AR signaling ameliorates the migration of prostate cancer cells via the up-regulation of annexin A1 expression." (PMID 36969009, 2023). "Androgens and androgen receptor (AR) signaling are essential for normal prostate development, the initiation of prostate cancer, and tumor progression even at very advanced stages." (PMID 37655657, 2023). "The androgen receptor (AR), a hormone-inducible transcription factor, represents an important therapeutic target in prostate cancer." (PMID 36674785, 2023). "As the imidazopyridines analyzed for the inhibition of clonal expansion of ER+ breast cancer cells also inhibited proliferation of AR+ prostate cancer cells, it is possibility that these compounds function through a common antitumor pathway." (PMID 37520743, 2023). "Knockdown of GABARAPL1, an early estrogen-regulated gene belonging to the GABARAP family, inhibits AR-positive prostate cancer growth." (PMID 36937439, 2023). "Typically, in HR + cancers, including ER + breast cancer and AR + prostate cancer, YAP/TAZ seem to perform a tumor-suppressive function through different mechanisms." (PMID 37211598, 2023). "AR plays an essential role in many diseases, including complete androgen insensitivity syndrome, spinal bulbar muscular atrophy, prostate cancer, and breast cancer." (PMID 36819777, 2023). "Similar to CRY1 in prostate cancer cells, polyQ-expanded AR bound AREs present in the promoters of Lsd1 and Prmt6 in SBMA myotubes." (PMID 36746939, 2023). "Currently, AR inhibitors are being widely used to treat prostate cancer and are showing encouraging results in TNBC." (PMID 38086377, 2023). "Similar to AR in prostate cancer, MYC is predominantly co-amplified with the adjacent regulatory region and/or the regulatory region is amplified alone." (PMID 37443779, 2023). "Current CRPC treatments focus on suppressing AR activity with antagonists like Enzalutamide/Apalutamide or reducing androgen production from the adrenal gland and prostate cancer cells with Abiraterone." (PMID 36776320, 2023). "Recent advancements have explored novel drugs that target the androgen receptor signaling pathway to inhibit the growth of prostate cancer." (PMID 37765058, 2023). "The AR pathway is the most frequently responsible for tumorigenesis and tumor growth in prostate cancers." (PMID 37021836, 2023). "Accordingly, our study suggested that a putative R1881/AR/MALT1/NF-κB-signaling pathway is involved in the regulation of PSA expression in ARFL-positive prostate cancer cells." (PMID 37047218, 2023). "In recent years, G3BP1 has been reported to promote the development of prostate cancer by inhibiting the degradation of AR through inhibiting SPOP." (PMID 37904149, 2023).
prostate carcinoma (continued). "Enzalutamide, as a second-generation endocrine therapy drug for prostate cancer (PCa), is prominent representative among the synthetic androgen receptor antagonists." (PMID 37008945, 2023). "We also demonstrated that inhibition of Sigma1 suppresses aberrant AR signaling in prostate cancer cells." (PMID 37874216, 2023). "AR is considered an oncogene in prostate cancer, thus, inhibiting AR can deter cell proliferation, allowing for tumor suppression." (PMID 38067367, 2023). "Prostate cancer cells with AR amplification can endure with androgen deprivation therapies, progressing to castration resistant prostate cancer (CRPC)." (PMID 36978046, 2023). "Androgen and androgen deprivation (castration) therapies, including androgen receptor antagonists, are clinically used to treat patients with prostate cancer." (PMID 37025180, 2023). "Prostate cancer-associated SPOP mutants (Y87C, Y87N, F102C, S119N, F125V, W131G, F133L, and F133V) fail to bind AR protein, thereby increasing the protein stability and activity of AR during tumorigenesis." (PMID 36776288, 2023). "In this study, TQB3720 promoted ferroptosis in prostate cancer cells by alleviating the AR/SP1 transcriptional complex." (PMID 36744249, 2023). "The splicing patterns of NUMB exon 3, MYO1B exon 23 and other ESRP-target exons can be experimentally modulated either by depleting ESRP1 and ESRP2 protein levels in prostate cancer cells, or by using drugs like Casodex to interfere with AR signalling." (PMID 37752235, 2023). "Hyperactive AR, in association with critical coactivators such as p300, BRD4, and MED1, drives prostate cancer progression." (PMID 37644036, 2023). "Early-stage prostate cancer requires androgens for growth and maintenance like normal prostate tissue, of which both are AR-dependent." (PMID 37744273, 2023). "The aberrant isoform of AR-V7 is constitutively active, thereby contributing to the development and progression of castration-resistant prostate cancer and resistance to AR-targeted therapy." (PMID 37342192, 2023). "The androgen receptor (AR) is an important drug target in prostate cancer and a driver of castration-resistant prostate cancer (CRPC)." (PMID 36674785, 2023). "In prostate cancers, androgen receptor (AR) overexpression allows the cancer cells to advance to androgen castration stages." (PMID 36978046, 2023). "It is known that AR knockdown inhibits prostate cancer cell growth in both androgen-sensitive and androgen-insensitive cell lines." (PMID 37830741, 2023). "In prostate cancer, activation of the AR drives cancer growth and accordingly is the pharmacological target of clinically approved antiandrogens." (PMID 36991452, 2023). "Proxalutamide was originally developed as an AR antagonist for advanced prostate cancer and is in ongoing phase 2 clinical trials for this indication as well (45, –47)." (PMID 37459541, 2023). "AR is a principal driver of prostate cancer progression and an important therapeutic target for all clinical stages of prostate cancer." (PMID 37744273, 2023). "The AR is a key factor in the differentiation of luminal epithelial cells and was shown to play a tumor-suppressive role in breast and prostate cancers." (PMID 37142586, 2023). "There is no report about the direct relationship between m6A modification and androgen receptor (AR)-related genes in prostate cancer (PC)." (PMID 38042806, 2023). "Expression levels of ESRP1 and ESRP2 genes also decrease in response to enzalutamide, a drug blocking AR function in prostate cancer cells." (PMID 37752235, 2023). "In this study, we demonstrated an association between AR inhibition and increased CHRM4 expression in various prostate cancer cell lines and clinical datasets." (PMID 37142586, 2023). "Its cistrome differs from that of full-length AR and also undergoes changes along prostate cancer progression." (PMID 36768610, 2023).